NF1 (neurofibromin 1)
Diseases named in the same sentence as NF1 in open-access papers (continued):
Sharing a sentence is not in itself a finding about the gene and the disease.
tumor (continued). "Patients with a suspicion of (symptomatic) PN regularly undergo regional MR imaging, and screening for PN tumor load with whole body-MRI (WB-MRI) is recommended in the NF1 guideline by the European Reference Network (ERN) of Genetic Tumor Risk Syndromes (GENTURIS)." (PMID 41464147, 2025). "NF1-associated PA are associated with increased microglia versus sporadic tumours." (PMID 39948623, 2025). "Therefore, there is a clear clinical need to discover new drugs that specifically target NF1‐deficient tumor cells either alone or in combination with selumetinib." (PMID 39129390, 2025). "A systematic literature search was conducted across PubMed, IEEE Xplore, Google Scholar, and ResearchGate to identify recent studies applying AI technologies to NF1 genetic analysis, focusing on variant interpretation, structural modeling, tumor classification, and therapeutic prediction." (PMID 40428382, 2025). "NF1 is a tumour predisposition syndrome and the most common NF1-associated tumours are benign peripheral nerve tumours that may be cutaneous neurofibromas (cNFs), subcutaneous neurofibromas (scNFs) or plexiform neurofibromas (pNFs)." (PMID 40759488, 2025). "A longitudinal whole-exome study of NF1-associated tumour evolution revealed progressive NF1 inactivation accompanied by telomere-associated genomic instability, highlighting telomere shortening and dysregulation of the shelterin complex as possible contributors to malignant transformation." (PMID 40843672, 2025). "Epigenetic modifications, including DNA methylation, histone alterations, miRNAs, and lncRNA, have been implicated in the pathogenesis of NF1, as well as in the regulation of tumour initiation, progression, and phenotypic heterogeneity, among NF1-associated neoplasms." (PMID 40843672, 2025). "Moreover, numerous dysregulated long non-coding RNAs (lncRNAs) and microRNAs (miRNAs) have been identified in NF1-associated malignancies and are recognized as potential tumor biomarkers." (PMID 41463204, 2025). "While the hypermethylation of tumour suppressor genes has been associated with a malignant transformation and poor prognosis in NF1-associated MPNSTs, evidence also highlights the role of gene-specific hypomethylation in promoting oncogenic signalling pathways." (PMID 40843672, 2025). "This may emphasize previous clinical observations of a limited coherency of radiologically detectable tumor growth behavior and changes of VA in these patients, and moreover point towards notable biological differences between sporadic and NF-1 associated OPG." (PMID 40643687, 2025). "Therefore, this methylation classifier represents a non-invasive, functional diagnostic tool for early NF1-associated tumor diagnosis and screening." (PMID 41463204, 2025). "Recent studies have highlighted intratumoral heterogeneity in NF1-associated tumors, particularly reflected by the stem-like tumor subpopulation, that may drive treatment resistance and recurrence in patients." (PMID 40723243, 2025). "Mutations within the NF1 gene, which is deemed a tumour suppressor, instigates the condition." (PMID 38859614, 2025). "In addition, deep learning models, such as LTC neural networks, support tumor classification and therapeutic outcome prediction, particularly in NF1-associated complications like congenital pseudarthrosis of the tibia (CPT)." (PMID 40428382, 2025). "In Nf1-deficient mice, increased macrophage infiltration correlates with disease severity, and to mimic the communication between tumor-associated macrophages (TAMs) and tumor cells, conditioned media (CM) from macrophages and NF1-deficient cells were used to model this interaction." (PMID 40563570, 2025).
tumor (continued). "Discrepancies between studies may reflect differences in the investigated cohorts (like NF1-associated vs. sporadic individuals), tumor grade, or the genomic platforms used." (PMID 41463204, 2025). "All tumours in the cohort were sporadic except for the single NF1-associated case." (PMID 39948623, 2025). "Importantly, the development of certain NF1-related features, particularly tumour formation, often requires a second somatic mutation, or a “second hit”, leading to bi-allelic inactivation of NF1 in specific cell populations." (PMID 40843672, 2025). "All patients underwent extensive molecular testing with next-generation sequencing (custom 462-gene panel) and copy number variation analysis and were deemed to have potential NF1-loss-driven tumors after a case discussion in a multidisciplinary molecular tumor board." (PMID 41170454, 2025). "Interestingly, SCs deficient in neurofibromin, encoded by the NF1 gene, are biomechanically incompatible, as they lack sensitivity to the biomechanical microenvironment, which likely plays a role in tumor initiation and progression." (PMID 40940747, 2025). "First, genomics remains the backbone of NF1-associated tumor evolution." (PMID 41463204, 2025). "NF1-associated tumors, including pNFs, cNFs, and MPNSTs, consist of multiple interacting cell types, and single-cell-type models fail to recapitulate the in vivo tumor microenvironment." (PMID 41294711, 2025). "In this work, we retrospectively analyze the impact of tumor burden and growth velocity assessed by sequential three-dimensional, MRI-based, semi-automated segmentation-based volumetry on long-term VA outcomes in a cohort NF1-associated and non-NF1-OPG." (PMID 40643687, 2025). "Epigenetic mechanisms such as DNA methylation and histone modifications may contribute to or mimic this second-hit event by functionally silencing the remaining wild-type NF1 allele, thereby facilitating tumour initiation and progression." (PMID 40843672, 2025). "In the context of NF1, the loss of the second copy of the NF1 gene along with cues from the heterozygous microenvironment leads to the development of a PN, which is a benign tumor that can cause pain, mobility dysfunction, and organ compromise, depending on the location." (PMID 39857962, 2025). "Intriguingly, two patients in the CNS LS-related tumor group were over 50 years old, suggesting that co-occurring autosomal dominant tumor-related genes, such as NF1 variants, may drive tumorigenesis in these patients." (PMID 41261115, 2025). "However, this study was limited to only four patients and, in general, mutations in NF1 or NRAS in NB tumours occur rarely." (PMID 41511287, 2025). "NF1-associated GBMs are a heterogeneous group of neoplasms driven by biallelic NF1 inactivation." (PMID 40277798, 2025). "Additionally, we saw no impact for genotype on the microglial content within our cohort except for the single NF1-associated tumour, which possessed the greatest overall proportion of IBA1+ cells across both samples." (PMID 39948623, 2025). "Thus, DRG enlargement in NF1 is likely to reflect tumour-related structural changes caused by diffuse tumour infiltration." (PMID 40437318, 2025). "NF1 was also a potential driver in a third tumor that harbored a probably pathogenic NF1 variant." (PMID 39208653, 2024). "NF1 is an autosomal dominant disorder with a high risk of tumor formation." (PMID 38282102, 2024). "Interestingly, the RNAseq analysis revealed that Nf1-deficient IF/+ adipocytes before tumor formation express more collagen and collagen modification genes, which are commonly associated as a feature of fibroblasts." (PMID 38799507, 2024).
tumor (continued). "Further identification of specific CSC markers within this population of cells may enable early detection and intervention to prevent NF1-associated tumor transformation and metastasis." (PMID 39518076, 2024). "As such, its loss represents an additional mechanism by which tumour cells might escape from death in NF1 deletion patients." (PMID 38448973, 2024). "Furthermore, studies using hiPSCs and murine models have revealed that Nf1 mutations increase neuronal excitability, exacerbating tumor progression in both the central and peripheral nervous system." (PMID 39217323, 2024). "RAS dysregulated cancer cells rely on a high turnover of mitochondria due to their susceptibility to oxidative stress-induced damage; likewise, NF1-deficient tumor cells with RAS dysregulation might also require rapid mitochondrial turnover." (PMID 39016685, 2024). "However, up to 50% of all MPNSTs occur in individuals with NF1, where the reported lifetime risk of developing these tumours is 8–13%." (PMID 39409887, 2024). "Schwann cells or their precursors are the origin of tumor cells in NF1-associated PNST." (PMID 37173460, 2024). "Both were effective at identifying NF1 protein loss in tumor specimens predicted to have genomic loss of NF1 but may also identify a subset of NF1-wildtype tumors with protein loss." (PMID 39472976, 2024). "The risk of developing this tumor is significantly higher in people with a family history of NF1." (PMID 38903359, 2024). "Notably, these collagen and matrix changes were observed weeks before tumor formation typically occurs in these Nf1-deficient glands." (PMID 38799507, 2024). "In contrast, tumor biology of NF1-associated PNST is clearly differentiated." (PMID 38603731, 2024). "First, we may be missing the short window of the tumor microenvironmental alterations that occur in the rapid tumor onset that occur in Nf1-deficient PS-20/+ and IF; PS-21/+ glands." (PMID 38799507, 2024). "NF1 is attributed to germline mutations in one of the two alleles of the tumor suppressor gene NF1 located on chromosome 17q11.2 and somatic loss of function in the second allele that results in tumor development." (PMID 38893191, 2024). "Additionally, a genetic mutation in the NF1 gene (1885G > A) and an amino acid variation (glycine 629 arginine) were identified in the heart blood and tumor tissue of the deceased." (PMID 39612400, 2024). "NF1 deficiency also resulted in an increased tumor-associated macrophages/microglia infiltration." (PMID 39963421, 2024). "In addition to having the highest tumor mutational burden of the genomic subtypes, NF1-mutant tumors also have the highest SV burden." (PMID 38758740, 2024). "Neurofibromin 1 (Nf1) is a tumor suppressor gene that encodes a RAS–guanosine triphosphatase–activating protein (RAS-GAP) that reduces RAS activity and inhibits mitogen-activated protein kinase 1/2–extracellular signal-regulated protein kinase 1/2 (Mek1/2-Erk1/2) downstream signaling." (PMID 38360927, 2024). "Patients with NF1 are particularly at risk for developing tumours that may present atypically, highlighting the need for clinicians to maintain a high index of suspicion in this population." (PMID 39655114, 2024). "Furthermore, in association with genetic predispositions such as NF1, tumours tend to be multifocal in origin and are increasingly more difficult to resect." (PMID 38299304, 2024). "Precocious puberty is commonly seen in tumours associated with NF1." (PMID 39816384, 2024). "NF1 is a tumor-suppressor gene, with mutations in this gene inherited in a recessive transmission." (PMID 39211690, 2024). "Understanding the signatures of cancer stem cells (CSCs) for NF1-associated tumors may facilitate the early detection of tumor progression." (PMID 39518076, 2024). "Notably, the minipig is unique among model organisms in that it exhibits spontaneous loss of NF1 heterozygosity, which drives tumor formation in humans." (PMID 39217323, 2024).
tumor (continued). "We hypothesized that a synthetic lethal screen with yeast cells that lack an NF1 ortholog would identify tool compounds that might be selective for NF1-deficient human tumor cells." (PMID 39016685, 2024). "NF1 has an incidence of ̃1/3500 and is caused by inactivation of the NF1 tumour suppressor." (PMID 40225167, 2023). "Moreover, the wide range of tumor subtypes and their diverse locations support the concept of loss of NF1 at early developmental stages in undifferentiated precursor cells." (PMID 37569527, 2023). "In addition, posterior tumor location and optic disc abnormality at the initiation of chemotherapy are risk factors for refractory/relapsed NF1-OPG and poor visual outcomes." (PMID 37830595, 2023). "However, loss of GRD activity in NF1 tumor cells facilitates the constitutively activated (i.e., GTP-bound) conformation of RAS and thus potentiates its functioning as an oncogene." (PMID 38201517, 2023). "SUZ12 gene loss in NF1 microdeletion is also involved in tumor formation." (PMID 36831419, 2023). "Based on a meta-analysis study, the frequency of NF1 somatic mutations in this tumor is 28%." (PMID 37627552, 2023). "NF1 gene mutation is the direct cause of NF1.Located on chromosome 17q11.2, NF1 is a tumor suppressor gene that encodes a neurofibromin, involved in the transduction cascade of multiple signals such as Ras/RAF/MEK/ERK, Akt/mTOR and AC/cAMP, and associated with cell proliferation and differentiation." (PMID 37226143, 2023). "The CNA profiles were similar between the NF1-associated and sporadic tumours, although there was a trend towards a higher burden of CNAs (P = 0.07), LOH (P = 0.05, both from Wilcoxon's test), and homozygous deletion of CDKN2A (OR = 2.4, P = 0.06 from Fisher's exact test) in NF1-associated tumours." (PMID 37837931, 2023). "In addition, the loss of the second Nf1 allele in astroglial progenitors alone is insufficient for tumor development: the interaction with the microenvironment is also crucial." (PMID 37830595, 2023). "In contrast to monocyte abolishment, decreased neutrophil recruitment results in extended survival of Nf1-silenced tumor-bearing mice, suggesting that driver mutations not only influence myeloid composition of tumor but also determine their biological function." (PMID 37012245, 2023). "The NF1 gene is a tumor pathogenic suppressor gene located on chromosome 17q11.2." (PMID 35702826, 2023). "Immune profiling of NF1-associated tumors by Haworth and colleagues highlighted the importance of understanding the immunogenicity of these tumors, especially in the context of tumor heterogeneity." (PMID 37817770, 2023). "An NF1 mutation was also detected in all tumours from patient B." (PMID 36882706, 2023). "NF1 is caused by mutations in NF1 (chromosome 17q11.2), the gene coding for neurofibromin 1, a negative regulator of the Ras signal transduction pathway that has a role in both tumor suppression and the regulation of cell growth and proliferation." (PMID 36980803, 2023). "Furthermore, there are few known differences in the molecular profiles of NF1-associated and sporadic tumours." (PMID 37837931, 2023). "Moreover, while paracrine effects and stromal cell recruitment are a part of all GBM subtypes, in tumors with mesenchymal signature and frequent loss of NF1 tumor suppressor gene the inflammatory stromal component is especially prominent." (PMID 38188342, 2023). "NF1, first described by the German pathologist Friedrich von Recklinghausen, is an autosomal-dominant disorder, which refers to autosomal dominant mutations in the NF1 tumor suppressor gene." (PMID 38138947, 2023). "It has also been reported that individuals with NF1 may have an increased susceptibility to other neoplasms." (PMID 37147639, 2023). "NF1 gene is a tumor suppressor gene with a high mutation rate and extreme mutation heterogeneity." (PMID 36246612, 2022).
tumor (continued). "Several studies showed that different mutations of NF1 and related genetic modifiers might contribute together to clinical features in NF1, including tumor development, making the scenario more complex." (PMID 35885913, 2022). "The first group (“molecular low-grade”) consisted of those 29 tumors with biallelic inactivation of the NF1 tumor suppressor gene only and one tumor with biallelic inactivation of NF1 plus an activating missense mutation in PTPN11, a phosphatase that regulates the MAP kinase signaling pathway." (PMID 35945463, 2022). "Accumulation of second NF1 hits occurring in rapidly proliferating cells (prone to accelerated NF1 mutation rate) may explain increased tumour load arising from a decreased MMR capacity in NF1." (PMID 34997843, 2022). "Unlike previous studies, after ruling out other potential genetic drivers, we detected a somatic de novo truncating mutation in the NF1 gene directly in his MTC tumor, and further confirmed the downstream outcome of this mutation at transcriptomic and proteomic levels." (PMID 36344509, 2022). "In order to investigate whether tumours carrying the NF1/DLST-p.Gly374Glu mutations showed other molecular features observed previously in DLST-mutated PPGLs, we carried out the IHC for DLST." (PMID 36760809, 2022). "In a word, in this study, first the mRNA and protein expression of NF1 was decreased in the UPS tumor tissue, and NF1 protein was associated with some clinical characteristic, such as tumor size, distant metastasis, and recurrence via the PI3K-Akt-mTOR-S6 signal pathway." (PMID 35559021, 2022). "However, one of the tumours carrying the double mutation in NF1/DLST exhibited an accumulation of cis-aconitate and a slightly high ketoglutarate/fumarate ratio was observed in the two NF1/DLST-mutated tumours compared to tumours carrying only an NF1 mutation." (PMID 36760809, 2022). "Thus, after Nf1 loss, transcriptional reprogramming in SCs, and activation of the NF-κB pathway, tumor formation/transcriptional reprogramming are observed in tumor immune cells and stroma." (PMID 36134665, 2022). "Our results show that PMS2 mutations often occur simultaneously with NF1 mutations, which may indicate the dedifferentiation tendency and high mutation load of this group of tumor cells." (PMID 35865459, 2022). "When considering neoplasms, carriers of variants falling in the extradomain region at the 5′ end of NF1 had a lower age‐related cancer frequency than the rest of the gene sequence, showing a borderline significance (p = 0.045), which was not conserved after correction with covariates." (PMID 34427956, 2022). "As a tumor suppressor gene, NF1 mutation may be more likely to lead to the occurrence of SBA under some mechanism." (PMID 36620543, 2022). "Thus, after Nf1 loss, transcriptional reprogramming in SCs and activation of the NF-κB pathway and tumor formation/transcriptional reprogramming in tumor immune cells and stroma are observed." (PMID 36134665, 2022). "In CMMRD associated tumours and other features, such café-au-lait spots, a second double NF1 hit leads to a biallelic NF1 inactivation which may be difficult to distinguish from mosaic or segmental NF1." (PMID 34997843, 2022). "In other studies, mutations of NF1 are the expression of a subpopulation of the tumor." (PMID 36289852, 2022). "Clinical trials have focused on drugs that may block directly or indirectly pathways that are overactivated by NF1 or NF2 tumor-suppressor mutations." (PMID 35291225, 2022). "However, it is notable that RASA2 is usually co-mutated with other tumor suppressors (such as NF-1), suggesting reduced transformation potential as a single mutation." (PMID 36002574, 2022).